ENSG00000280371 ( gene)
Diseases named in the same sentence as ENSG00000280371 in open-access papers (continued):
Sharing a sentence is not in itself a finding about the gene and the disease.
tumor (continued). "In this study we focused on the lncRNA, prostate cancer associated transcript 29 (PCAT29), a putative tumor suppressive gene." (PMID 28467474, 2017). "Expression of mutL homolog 1 (MLH1), a mismatch repair gene that corrects DNA replication errors, is lost in up to 15% of sporadic tumours due to mutation or, more commonly, due to DNA methylation of its promoter CpG island." (PMID 28293327, 2017). "Several studies have suggested the role of miR-340 as tumor suppressor gene, but one report demonstrated the association between miR-340 and chemoresistance." (PMID 29050253, 2017). "Based on current knowledge, it is still difficult to define HNRNPK as an oncogene or a tumor suppressor gene because of dichotomous results from clinical association data and cell line studies." (PMID 29262567, 2017). "Checkpoint with fork-head associated and ring finger (CHFR) is a mitotic checkpoint gene with tumor-suppressor functions." (PMID 24348823, 2014). "Our work suggests that Drosophila Rabex-5 is also a neoplastic tumour suppressor gene and that the tumour phenotype of both mutants is associated with ectopic activation of JNK and JAK/STAT pathways." (PMID 24104056, 2014). "ANX7 exhibits many biological and genetic properties of a tumor suppressor gene and is also implicated in carcinogenesis through discrete signaling pathways involving other tumor suppressors, DNA-repair and apoptosis-related genes." (PMID 22532868, 2012). "Recently, PLZF has become implicated in carcinogenesis as a tumor suppressor gene, because of its ability to regulate the cell cycle and apoptosis in many cell types." (PMID 22822476, 2012). "Emphasis should be placed on elucidating the exact relationship of TP with other angiogenic factors, HIF, signalling abnormalities, oncogene activation and loss of tumour suppressor gene function." (PMID 16317434, 2006). "Indeed, RB1 is classically and unambiguously implicated as a tumor suppressor gene for other cancer types by germline evidence." (PMID 41279109, 2025). "Even if a not negligible rate of patients with PTEN mutations do not meet diagnostic criteria for CS/PHTS, PTEN is known to be a tumor suppressor gene and the patients that show its mutation should be monitored because of the increased risk of developing malignancies." (PMID 36672590, 2022). "The role of Zbtb18 in these diseases is not well understood, but recent findings have shown that it may act as a tumor suppressor gene such that its loss may directly contribute to the development or progression of the disease." (PMID 33608456, 2021). "SLC39A10 which was down-regulated and positively associated with OS may act as a tumour suppressor gene in GBM." (PMID 32875483, 2020). "Each miRNA has a specific target mRNA, and the mRNA encoded by the tumor suppressor or tumor-promoting gene can affect the synthesis of some important cancer-associated functional proteins, so changes in mRNA expression can directly affect the occurrence of malignant tumors." (PMID 33336056, 2020). "As frequently observed for cancer-associated miRNAs, miR-494 may behave as an oncogene or a tumor-suppressor gene in a tissue-dependent manner." (PMID 29305580, 2018). "ARLTS1 is a cancer-associated gene with notable tumour suppressor properties." (PMID 28630657, 2017).
tumor (continued). "The deficiency of TIF1γ expression in a variety of tumor cells suggests that TIF1γ may play as a tumor suppressor gene in cancer development." (PMID 23676978, 2013). "Furthermore, it has been shown recently in a spontaneous model of intestinal tumorigenesis (driven by a heterozygote mutation in the tumor suppressor gene denomatous polyposis coli) that the ablation of IL-17 leads to inhibition of tumor development." (PMID 21943203, 2011). "Nearly half of these tumours arise in the context ofthe inherited predisposition syndrome, neurofibromatosis type 1 (NF1),suggesting that inactivation of the NF1 tumour suppressor gene might be causally related to the development of thesecancers." (PMID 18769552, 2008). "This suggests the target of allelic loss on 17q is a tumour-suppressor gene in this region." (PMID 7734302, 1995). "Since it is well established however that tumor development requires an accumulation of several gene mutations, we hypothesized that a potential OS suppressor function of Rptpζ can only be uncovered in the context of an already existing mutation of a common tumor suppressor gene." (PMID 26360410, 2015). "Fumarate hydratase (FH) is an enzyme involved in the tricarboxylic acid cycle and is a tumor suppressor gene." (PMID 40362376, 2025). "An analysis of literature data demonstrated that miRNA-23a can function both as an oncogene and as a tumor suppressor gene." (PMID 40282476, 2025). "In this study, we observed that NDRG1 exhibits an independent association with a more favorable prognosis in SKCM, suggesting its potential role as a tumor suppressor gene." (PMID 41409301, 2025). "AMBRA1 regulates multiple pathological processes in cancer cells, but the specific role it plays depends on the tumour microenvironment and genetic background, indicating that it can act as an oncogene or a tumour suppressor gene." (PMID 40464146, 2025). "miR-34c, a member of the miR-34 family, has been extensively investigated in cancer research as a tumor suppressor gene." (PMID 39129166, 2025). "GSDME is a key protein in the switch between apoptosis and cellular pyroptosis and has been identified as a potential tumor suppressor gene." (PMID 40756987, 2025). "SOD2 is a mitochondrial antioxidant gene that can be upregulated by the UPRmt, and it exhibits both tumor-suppressive and tumor-promoting functions through scavenging superoxide and regulating hydrogen peroxide levels." (PMID 41154474, 2025). "Discovered over 20 years ago as a “candidate tumor suppressor gene”, PTEN is an enzyme that is strictly regulated and capable of dephosphorylating both protein and lipid substrates." (PMID 40463389, 2025). "LHPP functions as a tumor suppressor gene in GC by regulating the PI3K/AKT/mTOR pathway and inhibiting the Wnt/β-catenin signaling pathway, the TGFβ/Smad signaling pathway, AKT phosphorylation, and other mechanisms to suppress tumor occurrence and progression." (PMID 40240758, 2025). "If the target of ncRNAs is an oncogene, ncRNAs can be considered a tumor-inhibiting factor; if the target of ncRNAs is a tumor suppressor gene, ncRNAs can be considered an oncogenic factor." (PMID 40296912, 2025). "We confirmed through machine learning residual analysis that TNNC1 is significantly downregulated in LUAD tissues, consistent with its function as a tumor suppressor gene." (PMID 40433361, 2025).
tumor (continued). "ERBB4 is also the only member of the EGFR family that can function as either an oncogene or a tumor suppressor gene." (PMID 37855863, 2024). "Taken together, these findings suggest that hnRNPA1 plays a different regulatory role and acts as a tumor suppressor gene in AGS and Kato III cells by regulating the formation of RONΔ160." (PMID 38268030, 2024). "KCNQ1 has also been demonstrated to act as a tumor suppressor gene in some gastrointestinal cancers." (PMID 38807370, 2024). "Our KEGG enrichment analysis of the transcriptome data also demonstrated that circSPECC1 functions as a tumor suppressor gene in GBM by primarily influencing the PI3K-AKT signaling pathway." (PMID 39333871, 2024). "It has been shown that pharmacological activation of PTEN, a potent tumor suppressor gene, can dominantly antagonize the proto-oncogenic phosphoinositide 3-kinase (PI3K)–AKT signaling pathway with acceptable side effects." (PMID 39502780, 2024). "Previous studies have suggested that TRIAP1 functions as a tumor-promoting gene, whereas LC3B acts as a tumor suppressor gene." (PMID 38769122, 2024). "Collectively, these results indicate that SESN1 is a downstream target of MYCN and functions as a tumor suppressor gene in NB." (PMID 38516781, 2024). "The results of this study suggested that CYLD acted as a tumor suppressor gene in PCa and promoted cell ferroptosis through Hippo/YAP signaling." (PMID 38246916, 2024). "In the context of tumor cells, Egr1 plays a dual role, functioning as both a tumor suppressor gene and a tumor-promoting gene." (PMID 38672136, 2024). "Apart from its role as a cell cycle regulator, p21 regulates DNA replication, repair, and apoptosis, and inhibits tumor growth as a tumor suppressor gene." (PMID 39684919, 2024). "VEGF is a hypoxia-responsive gene that plays a key role in the development of tumor neovascularization." (PMID 38200568, 2024). "Growing evidence in recent years has demonstrated that METTL3, an m6A methyltransferase that functions as both an oncogene and a tumor suppressor gene, plays an important role in various cancers development." (PMID 38012763, 2023). "The human fragile histidine triad (FHIT) gene is a tumor suppressor gene, and heterozygous deletion (LOH), homozygous deletion, and abnormal expression of the FHIT gene have been implicated in several types of human malignancy." (PMID 37749550, 2023). "Unlike other cyclins, which positively regulate the cell cycle, cyclin G2 (CCNG2) regulates cell proliferation as a tumor suppressor gene." (PMID 37204480, 2023). "Studies have shown that p38MAPK acts as a tumor suppressor gene, negatively regulating cell cycle progression and inducing cell cycle arrest in the G2/M phase, as well as apoptosis." (PMID 37476197, 2023). "In different solid tumors and in diverse tumor cell lines, MEG3 overexpression inhibits proliferation, hence it is used as a tumor suppressor gene." (PMID 37388937, 2023). "According to earlier studies, TUSC7 can serve as a tumor suppressor gene in several tumors via inhibiting the expression of such miRNAs as miR-10a, miR-211 and miR-23b." (PMID 38054829, 2023). "As a functional DDR is critical for maintaining genome integrity and preventing tumor development, SETD2 is considered as a putative tumor suppressor gene in cancers." (PMID 37759431, 2023). "There is solid evidence that TPM1 can act as a tumor-suppressor gene in oral squamous cell carcinoma (OSCC)." (PMID 37686101, 2023). "NLRP3 also has been reported in a multitude of studies to be involved in tumor growth and development both as an oncogene and as a tumor suppressor gene." (PMID 37449203, 2023). "Our previous experiments confirmed that NCX2 inhibited the growth of U87 cells in nude mice, indicating that NCX2 is a potential tumor suppressor gene." (PMID 36334237, 2023).
tumor (continued). "As a tumour suppressor gene, PTEN is a key negative regulator of the PI3K/AKT pathway, which is involved in regulating cell biological processes such as cell proliferation, invasion, and cycle arrest." (PMID 36908850, 2023). "Previous studies pointed out the potential of DAB2 as a tumor suppressor gene since a decrease in DAB2 expression was observed in a wide range of tumors." (PMID 37510211, 2023). "Although studies have shown the role of TBX2 as a tumor suppressor gene, there is some evidence correlating the overexpression of TBX2 in NSCLC." (PMID 37324026, 2023). "The PRDM5 protein was found to have a variety of functions as a transcription factor, being involved as a tumor suppressor gene in epithelial cancer and as a regulator of extracellular matrix development in corneal and bone cells." (PMID 37629506, 2023). "Mounting evidence showed that RRAD is important for the progression and metastasis of tumor cells, which play opposite roles as an oncogene or tumor suppressor gene depending on cancer and cell type." (PMID 36979412, 2023). "Theories of malignant transformation include synergistic effect of smoking and HPV infection, abnormal expression of genes such as tumor suppression gene." (PMID 37069678, 2023). "In vitro, we found that PTGIS was a tumor-promoting gene of LUSC and HRASLS was a tumor-suppressor gene." (PMID 36703911, 2023). "In this context, our study indicated the expression of function of a tumor-promoting gene, METTL13, in GC for the first time." (PMID 35925508, 2023). "Zinc finger, DHHC-type containing 2 (ZDHHC2), proposed as a putative tumour/metastasis suppressor gene and was often aberrantly decreased in human cancers." (PMID 35057823, 2022). "Inhibitor of growth family member 4 is a candidate tumour suppressor gene that exerts the tumour‐suppressive effect via multiple pathways in various tumours." (PMID 35075768, 2022). "Second, the number of included studies on circRNA, a tumor suppressor gene, is relatively small, and more studies need to be conducted in the future, to further confirm the results." (PMID 35595945, 2022). "TXNIP is a thioredoxin-binding protein involved in redox regulation and glucose uptake that functions as a tumor suppressor gene." (PMID 36137002, 2022). "Our current study supports a role for ZNF148 as a tumor suppressor gene in metastatic TNBC, that is actively repressed by MYC." (PMID 36207293, 2022). "Our findings differ from previous publications, one of which touted Notch1 as a tumor-promoting gene, whereas the other concluded Notch1 is a tumor-suppressor gene." (PMID 36970723, 2022). "Exogenous expression of the EMP3 gene has been found to limit tumor cell proliferation and act as a tumor suppressor gene." (PMID 35982458, 2022). "ATAC-seq reveals that it induces EPHA3, which is a tumor neoantigen and tumor-suppressor gene, thus demonstrating a novel mechanism of action." (PMID 35624662, 2022). "Although ZNF320 and CD8+ T cell infiltration are associated, we found that ZNF320 is positively correlated with the immune checkpoint gene, cannot produce tumor killing benefits, and is actually involved in immune escape." (PMID 36287187, 2022). "At early stages, TGFβ suppresses tumor growth, acting as a tumor suppressor gene, while during latest stages and in metastasis TGFβ enhances tumor growth and promotes angiogenesis, migration, and invasion." (PMID 36338516, 2022). "Lnc-RAB11B-AS1 is reported to be dysregulated in several types of cancers and can function as both an oncogene and tumor suppressor gene." (PMID 36359911, 2022). "This suggests that SMIM3 has complex regulatory roles, and can act as either a potential oncogene or a tumor suppressor gene in different cancer types." (PMID 36550462, 2022). "GSDME was shown to be sensitive to a number of anti-neoplastic drugs among others, which is reported to be suppressed via epigenetic inactivation in various cancers and considered as a tumor suppressor gene." (PMID 36605187, 2022).
tumor (continued). "AHRR encodes the aryl hydrocarbon receptor repressor (AhRR), which acts as a tumor suppressor gene in multiple human cancers." (PMID 35778420, 2022). "Interferon regulatory factor-5 (IRF5) is a transcription factor and has essential cellular mechanisms as a tumor suppressor gene." (PMID 35410350, 2022). "Based on the findings, including the results of in vitro tests, it was observed that DIRAS2 is a tumor suppressor gene for SKCM, with the Wnt/β-Catenin signaling pathway being the negatively regulated target." (PMID 35651810, 2022). "Recently, it has been verified that miR-153, as a tumor suppressor gene, regulates angiogenesis by modulating VEGF and ANG1 in glioma and breast cancer, respectively." (PMID 36158686, 2022). "Overall, our study demonstrated that LHPP function as a tumor suppressor gene in GC by regulating the PI3K/AKT/mTOR pathway." (PMID 36484014, 2022). "Recent studies have shown that the absence of SIRT1 can cause sphingomyelin to accumulate in cells, and in different cancer types or under different experimental conditions, SIRT can act as an oncogene or a tumor suppressor gene." (PMID 35846357, 2022). "MiR‐133b has been identified as a tumour suppressor gene in a variety of cancers, and is closely related to suppressed tumour metastasis." (PMID 35638462, 2022). "This review presents a study on the mechanistic roles of miR-153 as either a tumor suppressor gene or an oncogene in proliferation, apoptosis, migration and invasion, metastasis, angiogenesis and chemo/radio resistance ability of cancer cells." (PMID 36158686, 2022). "Taken together, these results show that PCBP1 acts as a tumour suppressor gene, inhibiting the tumorigenesis of LUAD." (PMID 35907982, 2022). "Recent studies have demonstrated that zinc-finger protein 677 (ZNF677) acts as a tumor suppressor gene in cancer." (PMID 35164660, 2022). "Taken together, these results reveal that PCBP1 acts as a tumour suppressor gene, inhibiting the tumorigenesis of LUAD." (PMID 35907982, 2022). "Pituitary tumor-transforming gene-1 (PTTG1), one type of DNA repair-related gene, has been reported to be dysregulated in several tumors and serve as a tumor promotor." (PMID 35251171, 2022). "Recent studies have highlighted the possible role of TRIM58 as a tumor suppressor gene, which degrades β-catenin through ubiquitination, resulting in the inactivation of β-catenin signaling." (PMID 36461099, 2022). "MicroRNAs (miRNAs) play a role in the development and progression of cancer as an oncogene or tumor suppressor gene." (PMID 35147974, 2022). "The GTP-binding protein Di-Ras3 (DIRAS3) has been established as a maternally imprinted tumor suppressor gene." (PMID 35170376, 2022). "RDH16 is a tumor-suppressing gene, and it had been reported that downregulation of RDH16 occurs in approximately 90% of primary HCC patients with poor prognosis." (PMID 35646665, 2022). "In this paper, we examined the status of GNMT, a gene identified in our previous studies as a putative tumor-suppressor gene and biomarker for PC." (PMID 33802396, 2021). "miR-182-5p as a gene with complicated functions can serve as an oncogene or a tumor suppressor gene in different cancers." (PMID 33959160, 2021). "In this study, we showed that GSK3β acts as a tumour suppressor gene; m6A‐modifed GSK3β was recognized and degraded by YTHDF2, leading to the activation of Wnt/β‐catenin signalling and further promoting the proliferation of CRC cells in vitro and in vivo." (PMID 34709763, 2021).